LMF2 (lipase maturation factor 2)
Description:
Involved in the maturation of specific proteins in the endoplasmic reticulum. May be required for maturation and transport of active lipoprotein lipase (LPL) through the secretory pathway (By similarity).
Synonyms: TMEM112B; TMEM153
Tractability: Antibody: UniProt predicts a signal peptide or a membrane-spanning region. PROTAC: ubiquitination databases record sites on it; its protein half-life has been measured.
Gene: Protein-coding gene on chromosome 22 (50,502,947 to 50,507,732, reverse strand). Ensembl gene ENSG00000100258.
Subcellular location: Endoplasmic reticulum membrane
Subcellular location (Human Protein Atlas): Centrosome
Pathways (Reactome):
Transport of small molecules: Assembly of active LPL and LIPC lipase complexes
Gene Ontology:
Molecular function: protein binding
Biological process: protein maturation
Cellular component: membrane; endoplasmic reticulum membrane
Genetic constraint (gnomAD): Loss-of-function variants: 110 observed, 76.97 expected, observed/expected ratio (o/e) 1.43, 90% interval 1.22 to 1.67. The synonymous counts are far from expectation, so gnomAD's model fits this gene poorly and the ratio says little. Missense variants: 1,139 observed, 807.98 expected, observed/expected ratio (o/e) 1.41, 90% interval 1.34 to 1.48. Synonymous variants: 599 observed, 366.74 expected, observed/expected ratio (o/e) 1.63, 90% interval 1.53 to 1.75.
Homologues: Orthologues: pig LMF2 (84% identical), mouse Lmf2 (82% identical), guinea pig LMF2 (82% identical), rat Lmf2 (81% identical), chimpanzee LMF2 (78% identical), rabbit LMF2 (74% identical), tropical clawed frog lmf2 (55% identical), zebrafish lmf2a (53% identical), zebrafish lmf2b (41% identical), Caenorhabditis elegans K11G12.6 (26% identical). Paralogues in human: LMF1 (24% identical).
Diseases named in the same sentence as LMF2 in open-access papers:
LMF2 is named in the same sentence as 4 diseases in open-access papers, as found by Europe PMC text mining. Sharing a sentence is not in itself a finding about the gene and the disease. The quoted sentences say what the papers report.
hippocampal atrophy (1 paper, 2021). "This is not consistent with observations from the previous research, showing a correlation between NCAPH2/LMF2 methylation and hippocampal atrophy in AD." (PMID 33603659, 2021).
LMF2 also shares sentences with these, for which no sentence is quoted: Alzheimer disease (1 paper); neurodevelopmental disorder (1); Obesity (1).